MIR450A2 (microRNA 450a-2)
Synonyms: hsa-mir-450-2; hsa-mir-450a-2; MIRN450-2; MIRN450A-2; MIRN450A2; mir-450a-2
Gene: MicroRNA gene on chromosome X (134,540,508 to 134,540,607, reverse strand). Ensembl gene ENSG00000207755.
Gene Ontology:
Biological process: miRNA-mediated post-transcriptional gene silencing
Cellular component: RISC complex
Homologues: Orthologues: chimpanzee ptr-mir-450a-2 (100% identical), macaque mml-mir-450a-2 (98% identical), guinea pig MIR450A2 (82% identical), rabbit MIR450A2 (76% identical), pig ssc-mir-450c (72% identical), mouse Mir450-2 (59% identical). Paralogues in human: MIR450A1 (79% identical), MIR450B (68% identical).